ZSCAN18 (zinc finger and SCAN domain containing 18)
Description:
May be involved in transcriptional regulation.
Synonyms: ZNF447; FLJ12895
Tractability: PROTAC: ubiquitination databases record sites on it.
Gene: Protein-coding gene on chromosome 19 (58,083,834 to 58,118,427, reverse strand). Ensembl gene ENSG00000121413.
Subcellular location: Nucleus
Subcellular location (Human Protein Atlas): Nucleoplasm; Basal body; Cytosol; Primary cilium
Gene Ontology:
Molecular function: protein binding; DNA-binding transcription factor activity, RNA polymerase II-specific; RNA polymerase II cis-regulatory region sequence-specific DNA binding
Biological process: regulation of transcription by RNA polymerase II
Cellular component: nucleus
Genetic constraint (gnomAD): Loss-of-function variants: 17 observed, 31.2 expected, observed/expected ratio (o/e) 0.54, 90% interval 0.37 to 0.82. The synonymous counts are far from expectation, so gnomAD's model fits this gene poorly and the ratio says little. Missense variants: 731 observed, 658.64 expected, observed/expected ratio (o/e) 1.11, 90% interval 1.04 to 1.18. Synonymous variants: 375 observed, 305.13 expected, observed/expected ratio (o/e) 1.23, 90% interval 1.13 to 1.34.
Homologues: Orthologues: chimpanzee ZSCAN18 (99% identical), macaque ZSCAN18 (92% identical), rabbit ZSCAN18 (64% identical), dog ZSCAN18 (54% identical), mouse Zscan18 (50% identical), rat Zscan18 (49% identical), Drosophila melanogaster CG12391 (11% identical), Drosophila melanogaster hb (9% identical), zebrafish plagl2 (8% identical), Caenorhabditis elegans hbl-1 (7% identical), zebrafish ovol1a (6% identical), Caenorhabditis elegans Y5F2A.4 (5% identical), and 3 more. Paralogues in human: ZNF446 (25% identical), ZNF202 (24% identical), ZSCAN1 (23% identical), ZKSCAN2 (23% identical), ZNF496 (22% identical), ZSCAN29 (21% identical), ZNF274 (21% identical), ZSCAN32 (19% identical), ZNF18 (19% identical), ZNF444 (18% identical), ZNF174 (16% identical), ZSCAN5A (15% identical), and 17 more.
Diseases named in the same sentence as ZSCAN18 in open-access papers:
ZSCAN18 is named in the same sentence as 14 diseases in open-access papers, as found by Europe PMC text mining. Sharing a sentence is not in itself a finding about the gene and the disease. The quoted sentences say what the papers report.
gastric cancer (2 papers, 2023). A primary or metastatic malignant neoplasm involving the stomach. "In a recent research of gastric cancer, methylation-silenced ZSCAN18 induces the proliferation via weakening TP53INP2-mediated autophagy." (PMID 37223020, 2023). "In a recent study, inactivation of ZSCAN18 by DNA methylation drives the proliferation via attenuating TP53INP2-mediated autophagy in gastric cancer." (PMID 37223020, 2023). "This study aims to investigate the roles of ZSCAN18 in gastric cancer (GC)." (PMID 36650573, 2023).
arterial diseases (1 paper, 2023). "However, relatively few studies have investigated the relevance of ZSCAN family proteins in human cancers, with the exception of the methylation status of ZSCAN18 in arterial diseases affecting the lower limbs and metal concentrations in maternal blood samples." (PMID 37223020, 2023).
breast carcinoma (1 paper, 2023). "However, the expression profile, epigenetic modification, prognostic value, transcription regulation, and molecular mechanism of ZSCAN18 in breast cancer (BC) remain unknown." (PMID 37223020, 2023).
Breast tumor (1 paper, 2024). "Breast tumor tissues have higher levels of ZSCAN18 DNA methylation than normal tissues." (PMID 38331927, 2024).
cervical cancer (1 paper, 2021). A primary or metastatic malignant neoplasm involving the cervix. "They identified 6 genes as the best candidate methylated biomarkers of cervical cancer progression (RGS7, LHX8, ST6GALNAC5, TBX20, KCNA3 and ZSCAN18)." (PMID 34882728, 2021).
gastric adenocarcinoma (1 paper, 2023). "Next, using IHC analysis, we semi-quantified ZSCAN18 protein levels of 83 fresh gastric adenocarcinoma tissues and matched adjacent non-tumor tissues." (PMID 36650573, 2023).
oropharyngeal squamous cell carcinoma (1 paper, 2019). "A cluster of Krüppel-type zinc finger protein genes (including ZNF132 and ZSCAN18, earlier known as ZNF447) on chromosome 19q13 was earlier found significantly epigenetically downregulated in oropharyngeal squamous cell carcinoma." (PMID 31796082, 2019).
renal cell carcinoma (1 paper, 2023). "A study of renal cell carcinoma found that ZSCAN18 knockdown promoted proliferation of human embryonic kidney cells and the demethylation drug azacitidine (Aza) reversed upregulation of ZSCAN18 protein expression in various renal cell carcinoma cell lines." (PMID 37223020, 2023).
cancer (6 papers, 2014 to 2023). A tumor composed of atypical neoplastic, often pleomorphic cells that invade other tissues. "Correlation analysis revealed that ZSCAN18 expression/methylation was strongly associated with infiltration of immune cells in multiple human cancers." (PMID 37223020, 2023). "Therefore, previous studies have linked ZSCAN18 to the development of various human cancers." (PMID 37223020, 2023). "Recently, hypermethylation in the promoter of ZSCAN18 has been identified in various types of cancers, such as esophageal cancer, renal cell carcinoma, cholangiocarcinoma, colorectal cancer, GC, hepatocellular carcinoma, and pancreatic cancer." (PMID 36650573, 2023). "TCGA dataset was referenced to determine the mRNA expression profiles and potential roles of ZSCAN18 in multiple types of cancer." (PMID 37223020, 2023). "ZSCAN18 methylation is prevalent and negatively correlated with expression in multiple human cancers, and the potential of ZSCAN18 methylation as a marker for tumor diagnosis and prognosis has been discovered." (PMID 37223020, 2023). "Zinc finger and SCAN domain-containing protein 18 (ZSCAN18) has been investigated as a putative biomarker of multiple human cancers." (PMID 37223020, 2023). "Our group previously reported that ZSCAN18 mRNA expression was downregulated in a variety of malignant tumors, including BC, suggesting an important role as a tumor suppressor gene." (PMID 37223020, 2023). "Seven genes are hypermethylated in ten cancer sites: six encoding zinc finger transcription factors (ZNF135, ZNF354C, ZNF415, ZNF542, ZNF671, ZSCAN18) and one encoding a transmembrane protein (TMEM25)." (PMID 25631659, 2015). "Initially, bioinformatics analysis of the data from The Cancer Genome Atlas (TCGA) datasets showed that expression of ZSCAN18 was depressed in a variety of cancers, and analysis from the public datasets (GSE33335) showed that ZSCAN18 is downregulated in GC samples." (PMID 36650573, 2023). "Tumor size, depth of tumor invasion (pT3–4 vs pT1-2), lymph node metastasis (positive vs negative) and low expression of ZSCAN18 predicted an increased risk of cancer-related death in univariate analysis." (PMID 36650573, 2023). "ZSCAN18 inhibits malignant behavior in GC by binding to the TP53INP2 promoter region and promoting autophagy, which may contribute to the development of a promising target for carcinoma diagnosis and treatment." (PMID 36650573, 2023).
tumor (4 papers, 2014 to 2023). "To gain insights into the molecular mechanisms underlying the tumor inhibition of ZSCAN18, we analyzed the downstream signaling pathways modulated by ZSCAN18 through RNA next-generation sequencing (RNA-seq) in ZSCAN18-overexpressed and control NCI-N87 cells." (PMID 36650573, 2023). "The most enriched tumor-associated processes associated with low expression of ZSCAN18 were identified based on the NES, which included the cell cycle (NES = 1.952; FDR q-value = 0.025, < 0.05) and glycolysis signaling pathway (NES = 1.966; FDR q-value = 0.034, < 0.05)." (PMID 37223020, 2023). "ZSCAN18 is a potential tumor suppressor in BC, as expression is modified by DNA methylation and associated with patient survival." (PMID 37223020, 2023). "Taken together, these results confirm the crucial role of ZSCAN18 as a functional anti-tumor gene through suppression of cell proliferation in GC." (PMID 36650573, 2023). "We elucidated the molecular mechanism of the tumor-suppressive function of ZSCAN18: regulation of the autophagy signaling pathway." (PMID 36650573, 2023). "The tumor volumes were 52.67 ± 13.58 mm3 in xenografted mice with ZSCAN18-overexpressed NCI-N87 cells and 167.7 ± 10.89 mm3 in xenografted mice with empty vector control NCI-N87 cells." (PMID 36650573, 2023). "Meanwhile, the TPM of ZSCAN18 was lower in primary tumor tissues (n = 1097) than normal tissues (n = 114) from TCGA samples, as determined with the UALCAN data analysis portal (p = 0.007, < 0.01)." (PMID 37223020, 2023). "The TIMER web server was used to compare the mRNA expression patterns of ZSCAN18 in tumor and adjacent normal tissues." (PMID 37223020, 2023). "The results of the present study highlight the potential of ZSCAN18 expression/DNA methylation in regulation of the tumor immune microenvironment in BC." (PMID 37223020, 2023). "The results showed that the extent of methylation of the ZSCAN18 promoter was significantly higher in primary tumor tissues (n = 793) than normal tissues (n = 97) (p < 0.001)." (PMID 37223020, 2023). "Subsequently, we compared the mRNA expression of ZSCAN18 in 30 GC tissue samples and matched adjacent non-tumor tissue samples by qRT-PCR." (PMID 36650573, 2023). "The Log2 standardized mRNA level of ZSCAN18 was lower in tumor tissues (n = 1038) than healthy and tumor-adjacent tissues (n = 92 and 104, respectively) (p < 0.0001)." (PMID 37223020, 2023). "The tumor growth was significantly lower in ZSCAN18-transfected nude mice than in the vector control mice, suggesting that ZSCAN18 does function as a tumor suppressor in GC." (PMID 36650573, 2023). "Functionally, ZSCAN18 overexpression inhibited the biological progression of GC cells, which was characterized by weaken proliferation, enhanced autophagy and suppressed tumor growth." (PMID 36650573, 2023). "Additional multivariate analysis showed that ZSCAN18 promoter hypermethylation in CpG45.46, depth of tumor invasion (pT3–4 vs pT1-2) and lymph node metastasis (positive vs negative) were independent prognostic factors." (PMID 36650573, 2023). "The level of ZSCAN18 methylation was investigated in 97 primary GC tissues and 6 adjacent non-tumor tissues by MassARRAY analysis, which identified significantly higher methylation of ZSCAN18 in GC." (PMID 36650573, 2023). "Aberrant ZSCAN18 promoter hypermethylation in various CpG islands (CpG11.19.39, CpG23.37.44, CpG26.27 and CpG45.46) was detected more often in GC tissues than in adjacent non-tumor tissues." (PMID 36650573, 2023).
tumor (continued). "IHC demonstrated that ZSCAN18 was positively stained in the nuclei of gastric mucosal cells and that its protein levels were considerably lower in GC tissues than in matched adjacent non-tumor tissues." (PMID 36650573, 2023). "Hence, additional studies are urgently needed to validate the findings of this study of the role of ZSCAN18 as a tumor suppressor in BC." (PMID 37223020, 2023). "In addition, decreased tumor growth resulting from ZSCAN18 overexpression was observed in nude mice and supports the inhibitory role of ZSCAN18 in GC." (PMID 36650573, 2023). "Furthermore, the tumor-suppressive function of ZSCAN18 in GC was investigated both in vitro and in vivo." (PMID 36650573, 2023). "In addition, ZSCAN18 plays important roles in transcription regulation, the glycolysis signaling pathway, and the tumor immune microenvironment." (PMID 37223020, 2023). "In summary, ZSCAN18 is a potential prognostic and methylation-regulated tumor biomarker in BC." (PMID 37223020, 2023). "Thus, it is urgent to explore the mechanism and function of ZSCAN18 transcriptional expression/DNA methylation in regulation of the tumor microenvironment." (PMID 37223020, 2023). "Furthermore, the restorability of CpG44.45 after treatment with DAC (also known as decitabine, a chemotherapy agent) indicates that ZSCAN18 may be a potential target for an anti-tumor drug." (PMID 36650573, 2023). "However, it remains unclear whether ZSCAN18 is involved in the tumor immune microenvironment in BC." (PMID 37223020, 2023). "By Cox proportional-hazards regression, two probes were statistically significant indicators, but were both less significant than tumor grade; BNC1 (p = 0.050, HR = 1.76, CI = 1.00–3.08) and ZSCAN18 (p = 0.028, HR = 1.87, CI = 1.07–3.24)." (PMID 24454902, 2014). "Multivariate analysis revealed that depth of tumor invasion (pT3–4 vs pT1-2), lymph node metastasis (positive vs negative) and expression of ZSCAN18 were independent prognostic factors." (PMID 36650573, 2023). "ZSCAN18 acted as a transcription factor and played an important role in binding to the promoter of tumor protein 53-induced nuclear protein 2 (TP53INP2), and we also confirmed the anti-tumor effect of TP53INP2 in GC." (PMID 36650573, 2023). "Accordingly, ZSCAN18 was downregulated significantly in the primary tumor compared to that in the adjacent non-tumor tissues." (PMID 36650573, 2023).
ZSCAN18 also shares sentences with these, for which no sentence is quoted: adenoma (1 paper); cancers of the esophagus (1); hepatocellular carcinoma (1); oral lichen planus (1).